SPRYD4 (SPRY domain containing 4)
Synonyms: DKFZp686N0877
Tractability: PROTAC: its protein half-life has been measured.
Gene: Protein-coding gene on chromosome 12 (56,468,578 to 56,479,708, forward strand). Ensembl gene ENSG00000176422.
Subcellular location (Human Protein Atlas): Nucleoplasm
Gene Ontology:
Molecular function: protein binding
Cellular component: mitochondrion; nucleus
Genetic constraint (gnomAD): Loss-of-function variants: 12 observed, 18.05 expected, observed/expected ratio (o/e) 0.66, 90% interval 0.43 to 1.08. The upper end of that interval is the gene's LOEUF score, 1.08, which puts it in group 4 of 6, group 1 being the genes least tolerant of losing a copy. Missense variants: 260 observed, 275.96 expected, observed/expected ratio (o/e) 0.94, 90% interval 0.85 to 1.04. Synonymous variants: 98 observed, 110.85 expected, observed/expected ratio (o/e) 0.88, 90% interval 0.75 to 1.05.
Homologues: Orthologues: chimpanzee SPRYD4 (100% identical), macaque SPRYD4 (98% identical), pig SPRYD4 (91% identical), dog SPRYD4 (89% identical), guinea pig SPRYD4 (89% identical), rabbit SPRYD4 (89% identical), mouse Spryd4 (85% identical), rat Spryd4 (84% identical), tropical clawed frog SPRYD4 (57% identical), zebrafish spryd4 (54% identical). Paralogues in human: RNF135 (20% identical), RFPL1 (16% identical), RFPL2 (16% identical), RFPL3 (16% identical), RFPL4A (16% identical), RFPL4AL1 (16% identical), RFPL4B (14% identical), RNF152 (14% identical), CD80 (5% identical), CD274 (5% identical), CD86 (4% identical), PDCD1LG2 (4% identical).
Diseases named in the same sentence as SPRYD4 in open-access papers:
SPRYD4 is named in the same sentence as 9 diseases in open-access papers, as found by Europe PMC text mining. Sharing a sentence is not in itself a finding about the gene and the disease. The quoted sentences say what the papers report.
cholangiocarcinoma (2 papers, 2023 to 2025). A carcinoma that arises from the intrahepatic biliary tree (intrahepatic cholangiocarcinoma) or from the junction, or adjacent to the junction, of the right and left hepatic ducts (hilar cholangiocarcinoma). "Lastly, the role of under-expressed SPRYD4 is less defined, though its over-expression in cholangiocarcinoma leads to cell cycle arrest and apoptosis, while knockdown of this gene causes the opposite effect, suggesting a role in cell cycle regulation and apoptosis." (PMID 39941055, 2025).
Alzheimer disease (1 paper, 2025). A progressive, neurodegenerative disease characterized by loss of function and death of nerve cells in several areas of the brain leading to loss of cognitive function such as memory and language. "Additional colocalisation was identified between the ratio of histidine-to-glutamine, glutamine, Alzheimer’s disease and SPRYD4 gene expression on chromosome 12." (PMID 40457327, 2025).
diabetic nephropathy (1 paper, 2023). "For example, while INHBC was known to be genetically associated with eGFRcr and upregulated in patients with diabetic nephropathy, the neighboring association of SPRYD4 was less well studied, with only one study finding higher expression in kidney tissue." (PMID 37365616, 2023).
lung squamous cell carcinoma (1 paper, 2023). "Additionally, patients with low SPRYD4 expression also had poor OS in other cancer types including kidney renal clear cell carcinoma (KIRC), liver hepatocellular carcinoma (LIHC), pancreatic adenocarcinoma (PAAD) and lung squamous cell carcinoma (LUSC)." (PMID 37142983, 2023).
tumor (4 papers, 2020 to 2025). "To further investigate the role of SPRYD4 in tumour immune infiltration, we evaluated the associations between SPRYD4 expression and immunostimulators or immunoinhibitors." (PMID 37142983, 2023). "SPRYD4 also showed a close association with tumour-infiltrating lymphocytes and important immune checkpoints including PD1, PD-L1 and CTLA4 in CCA." (PMID 37142983, 2023). "Moreover, low SPRYD4 expression in CCA was also associated with poor tumour differentiation, positive lymph node metastasis and advanced TNM stage." (PMID 37142983, 2023). "Functional enrichment analysis indicated that SPRYD4 may be involved in immune reactions; therefore, we explored the association between SPRYD4 expression and tumour immune infiltration in CCA." (PMID 37142983, 2023). "HUCCT1 SPRYD4-OV and control cells were injected in BALB/c-nude mice and a xenograft mouse model was constructed to assess the influences of SPRYD4 on tumour growth in vivo." (PMID 37142983, 2023). "The downregulation of SPRYD4 in CCA was significantly correlated with poor tumour differentiation, positive lymph node metastasis and advanced TNM stage." (PMID 37142983, 2023). "Collectively, the in vivo experiments indicated that the over-expression of SPRYD4 inhibited CCA tumour growth in vivo." (PMID 37142983, 2023). "Lower SPRYD4 expression has been previously linked to lower survival in cancer while higher levels of its encoded protein, SPRY-domain containing protein 4, are suggested to inhibit tumour growth through apoptosis." (PMID 40457327, 2025). "Furthermore, the RT-qPCR assay of 20 fresh CCA and normal bile duct tissues revealed that the mRNA levels of SPRYD4 were downregulated in the tumour tissues." (PMID 37142983, 2023). "Additionally, the tumour-inhibitory effect of SPRYD4 was validated in vivo using xenograft mouse models." (PMID 37142983, 2023). "Additionally, IHC assays indicated a high expression of Ki-67 in SPRYD4-OV tumour tissues, while a high expression of Tunel was observed in the control group." (PMID 37142983, 2023). "The over-expression of SPRYD4 significantly suppressed tumour growth rate 50 days after injection." (PMID 37142983, 2023). "Furthermore, the tumour-inhibitory effect of SPRYD4 was validated in vivo using xenograft mouse models." (PMID 37142983, 2023). "Moreover, a strong correlation between SPRYD4 expression and tumour immune infiltration was also demonstrated." (PMID 37142983, 2023). "Notably, SPRY-domain containing protein 4 (SPRYD4), a protein encoded by the SPRYD4 gene, has been demonstrated to serve as a tumour suppressor in HCC and inhibit tumour cell growth by inducing apoptosis." (PMID 37142983, 2023). "Moreover, a significant decrease in tumour weight in the SPRYD4-OV group was observed at the end of the experiment compared to the control group." (PMID 37142983, 2023). "However, it is plausible that the apoptotic mechanisms by which SPRYD4 inhibits tumour growth may contribute to neurodegeneration." (PMID 40457327, 2025). "Thus, SPRYD4, a tumour suppressor, can be a potential indicator for CCA prognosis." (PMID 37142983, 2023). "In conclusion, this study elucidated the role of SPRYD4 during CCA development and highlighted SPRYD4 as a novel biomarker and tumour suppressor in CCA." (PMID 37142983, 2023). "In addition to chaperones, which were shown to play a significant role for the induction of anti-tumor immune responses, we identified a number of TAAs interacting with NS1 (i.e., TPT1, NUMA1, SPRYD4, SND1, and GNL3)." (PMID 36680249, 2023).
cancer (2 papers, 2023 to 2025). A tumor composed of atypical neoplastic, often pleomorphic cells that invade other tissues. "The GEPIA database suggested that SPRYD4 expression was downregulated in some cancer types especially CCA." (PMID 37142983, 2023). "Bioinformatics analyses were performed to evaluate the differential expression of SPRYD4 in several cancer types." (PMID 37142983, 2023). "SPRY-domain containing protein 4 (SPRYD4) contains SPRY domains that modulate protein–protein interaction in various biological processes; however, its role in cancer development is insufficiently explored." (PMID 37142983, 2023).
SPRYD4 also shares sentences with these, for which no sentence is quoted: dementia (1 paper); dyslipidemia (1); pancreatic adenocarcinoma (1).